GNPTG (N-acetylglucosamine-1-phosphate transferase subunit gamma)
Description:
Non-catalytic subunit of the N-acetylglucosamine-1-phosphotransferase complex, an enzyme that catalyzes the formation of mannose 6-phosphate (M6P) markers on high mannose type oligosaccharides in the Golgi apparatus. Binds and presents the high mannose glycans of the acceptor to the catalytic alpha and beta subunits (GNPTAB). Enhances the rate of N-acetylglucosamine-1-phosphate transfer to the oligosaccharides of acid hydrolase acceptors.
Synonyms: C16orf27; GNPTAG; CAB56184; LP2537; c316G12.3; RJD9
Tractability: Antibody: UniProt places it where antibodies can reach, with high confidence; UniProt predicts a signal peptide or a membrane-spanning region; its Gene Ontology location is reachable by antibodies, with medium confidence. PROTAC: ubiquitination databases record sites on it; its protein half-life has been measured.
Gene: Protein-coding gene on chromosome 16 (1,351,931 to 1,365,737, forward strand). Ensembl gene ENSG00000090581.
Subcellular location: Secreted; Golgi apparatus
Subcellular location (Human Protein Atlas): Endoplasmic reticulum; Cytosol
Gene Ontology:
Molecular function: protein binding; protein homodimerization activity
Biological process: carbohydrate phosphorylation; N-glycan processing to lysosome
Cellular component: extracellular exosome; Golgi apparatus; UDP-N-acetylglucosamine-lysosomal-enzyme N-acetylglucosaminephosphotransferase complex; extracellular region
Genetic constraint (gnomAD): Loss-of-function variants: 47 observed, 43.77 expected, observed/expected ratio (o/e) 1.07, 90% interval 0.85 to 1.37. The synonymous counts are far from expectation, so gnomAD's model fits this gene poorly and the ratio says little. Missense variants: 549 observed, 410.37 expected, observed/expected ratio (o/e) 1.34, 90% interval 1.25 to 1.44. Synonymous variants: 250 observed, 173.08 expected, observed/expected ratio (o/e) 1.44, 90% interval 1.3 to 1.6.
Gene-disease validity (ClinGen):
ClinGen rates the evidence that GNPTG causes each of these diseases.
GNPTG-mucolipidosis (autosomal recessive): Definitive.
Homologues: Orthologues: chimpanzee GNPTG (96% identical), macaque GNPTG (94% identical), guinea pig GNPTG (79% identical), mouse Gnptg (79% identical), pig GNPTG (76% identical), tropical clawed frog gnptg (58% identical), zebrafish gnptg (54% identical). Paralogues in human: PRKCSH (19% identical).
Diseases named in the same sentence as GNPTG in open-access papers:
GNPTG is named in the same sentence as 26 diseases in open-access papers, as found by Europe PMC text mining. Sharing a sentence is not in itself a finding about the gene and the disease. The quoted sentences say what the papers report.
mucolipidosis type II (8 papers, 2015 to 2025). Mucolipidosis II (MLII) is a slowly progressive lysosomal disorder characterized by growth retardation, skeletal abnormalities, facial dysmorphism, stiff skin, developmental delay and cardiomegaly. "We performed whole exome sequencing in the proband to test for variants in the GNA11 and AP2S1 genes (less common causes of NSHPT) and also analyzed GNPTG as hyperparathyroidism and periosteal changes also occur in I‐cell disease (mucolipidosis Type II)." (PMID 30144375, 2018). "Mutations in GNPTAB and GNPTG genes could cause mucolipidosis types II and III, which are severe forms of autosomal recessive lysosomal storage diseases." (PMID 25643770, 2015). "However, it was hypothesized that GNPTAB and GNPTG variations involved in stuttering differ from the—mostly truncating—mutations reported in mucolipidosis II and III." (PMID 36618124, 2021). "N-acetylglucosamine-1-phosphotransferase subunit gamma (GNPTG) and N-acetylglucosamine-1-phosphotransferase subunit gamma (YOD1) are classically associated with mucolipidosis II/III and cancer, respectively." (PMID 38898508, 2024). "Mucolipidosis types II and III are severe forms of autosomal recessive lysosomal storage diseases that can be caused by mutations in the GNPTG gene." (PMID 37576559, 2023). "Homozygous loss of function variants in GNPTG causes gamma‐type mucolipidosis III (MIM 252605) and GNPTAB causes alpha‐beta type mucolipidosis II (MIM 252500) and III (MIM 252600)." (PMID 36618124, 2021). "Mucolipidosis II/III (OMIM 252500, 252600 and 252605) is caused by a lack of active enzyme GlcNAc-1-phosphotransferase (GNPTAB, GNPTG, EC 2.7.8.17), which is involved in the phosphorylation step in the synthesis of the mannose 6-phosphate marker present on the lysosomal membrane." (PMID 33669444, 2021).
mucolipidosis (5 papers, 2017 to 2023). A group of inherited lysosomal storage diseases characterized by accumulation of lipids and carbohydrates in the tissues, resulting in mental disabilities and skeletal malformations. "Pathogenic variants in GNPTAB and GNPTG, encoding different subunits of GlcNAc-1-phosphotransferase, cause mucolipidosis (ML) II, MLIII alpha/beta, and MLIII gamma." (PMID 34341521, 2021). "In family E, a variant in the mucolipidosis-associated gene GNPTG segregated with the phenotype." (PMID 37772257, 2023). "Hence, to study the impact of the de novo heterozygous missense variant identified in GNPTG, (a) quantification of mRNA by RT‐PCR, (b) activity of lysosomal enzymes in plasma, (c) mucolipidosis screening was carried out between the affected and unaffected members of the family." (PMID 36618124, 2021). "Diseases associated with GNPTG include mucolipidosis III gamma and mucolipidosis, and those associated with PERCC1 include diarrhea 11, malabsorptive, congenital, and hepatocellular carcinoma." (PMID 35990977, 2022).
lysosomal storage disease (2 papers, 2015 to 2020). A metabolic disorder caused by mutations in proteins critical for lysosomal function, including lysosomal enzymes, lysosomal integral membrane proteins, and proteins involved in the post-translational modification and trafficking of lysosomal proteins. "Mucolipidosis type III (MLIII) gamma is a rare inherited lysosomal storage disorder caused by mutations in GNPTG encoding the γ-subunit of GlcNAc-1-phosphotransferase, the key enzyme ensuring proper intracellular location of multiple lysosomal enzymes." (PMID 33023972, 2020).
mucolipidosis III (2 papers, 2020 to 2021). "The importance of heterozygous allele in GNPTG gene and its relevance in dysfluency disorder, as opposed to the reported recessive mucolipidosis III phenotype due to homozygous truncation of the same GNPTG gene was investigated." (PMID 36618124, 2021).
mucolipidosis III gamma (2 papers, 2022 to 2023). "Surprisingly, genetic testing revealed compound heterozygous pathogenic variants in GNPTG, leading to the diagnosis of the autosomal recessive lysosomal storage disorder mucolipidosis type III gamma." (PMID 37752499, 2023).
COVID-19 (1 paper, 2025). A disease caused by infection with severe acute respiratory syndrome coronavirus 2. "Conversely, GNPTAP and GNPTG, which are key enzymes involved in mannose-6-phosphate formation and lysosomal targeting, were down-regulated in the COVID-19(+) group." (PMID 39988192, 2025).
diabetes (1 paper, 2023). "One participant who was suspected of having syndromic diabetes had a pathogenic variant in the GNPTG gene, confirming a diagnosis of mucolipidosis gamma." (PMID 37897565, 2023).
dyslexia (1 paper, 2015). A learning disorder characterized by an impairment in processing written words. "In GNPTG, we genotyped 2 Tag SNPs and only found one SNP significantly associated with dyslexia before adjustment." (PMID 25643770, 2015). "As previous study reported association of GNPTAB, GNPTG and NAGPA with stuttering, we investigated these genes with dyslexia through association analysis." (PMID 25643770, 2015).
fronto-temporal dementia (1 paper, 2020). "In other neurodegenerative diseases, there is the strong association of heterozygous variants of PGN, the progranulin gene with fronto-temporal dementia and variants of GNPTAB, GNPTG, and the functionally related NAGPA gene with non-syndromic stuttering." (PMID 33005626, 2020).
lymphoma (1 paper, 2024). A malignant (clonal) proliferation of B- lymphocytes or T- lymphocytes which involves the lymph nodes, bone marrow and/or extranodal sites. "Five noninvasive biomarkers (FLT4, SFTPB, GNPTG, F5, and IL-17A) were further validated in an independent lymphoma cohort (n = 39), and another three noninvasive biomarkers (KIT, CCL3, and TNFSF1) were validated in NSCLC cohort (n = 76)." (PMID 38349411, 2024). "To address this question, we validated eight plasma proteins (IL-17A, F5, FLT4, SFTPB, and GNPTG in lymphoma, TNFSF12, CCL3, and KIT in NSCLC) for response prediction and three plasma proteins (IL36G, SERPINC1, and LTA) for relapse monitoring." (PMID 38349411, 2024). "To identify specific predictive biomarkers, we selected five biomarkers (F5, FLT4, GNPTG, IL-17A, and SFTPB) that were differentially expressed between the R and NR patient groups in both lymphoma cohorts from the top 20% of significantly differentially expressed proteins (p < 0.05)." (PMID 38349411, 2024).
retinitis pigmentosa (1 paper, 2023). Retinitis pigmentosa (RP) is an inherited retinal dystrophy leading to progressive loss of the photoreceptors and retinal pigment epithelium and resulting in blindness usually after several decades. "Here we describe a case of late-onset retinitis pigmentosa where genetic testing surprisingly identified two pathogenic variants in GNPTG, leading to the diagnosis of MLIII gamma." (PMID 37752499, 2023).
speech disorder (1 paper, 2025). A term referring to disorders characterized by the disruption of normal speech. "Mutations in NAGPA, GNPTG, and GNPTAB have been associated with the speech disorder in Pakistani family members." (PMID 39857822, 2025).
stuttering disorder (1 paper, 2023). "It has been reported that point mutations in highly conserved locations in GNPTAB, GNPTG, and NAGPA genes were linked to stuttering disorders." (PMID 38020803, 2023). "It has been shown that specific point mutations in four genes that are involved in the lysosomal enzyme-targeting pathway (i.e., GNPTAB, GNPTG, NAGPA, and AP4E1) are linked to stuttering disorder, in which they may contribute to up to 20% of the cases (Frigerio;Domingues and Drayna, 2017)." (PMID 38020803, 2023).
autosomal recessive disease (1 paper, 2023). Autosomal recessive form of disease. "Mucolipidosis II and III (MLII and MLIII) are autosomal recessive diseases caused by pathogenic variants in GNPTAB and GNPTG genes that lead to defects in GlcNAc-1-phosphotransferase." (PMID 38047750, 2023).
tumor (1 paper, 2022). "The functions of BCDIN3D, ZNF668, and GNPTG in tumor are poorly studied." (PMID 36470859, 2022).
GNPTG also shares sentences with these, for which no sentence is quoted: cancer (1 paper); dilated cardiomyopathy (1); hepatocellular carcinoma (1); hyperopia (1); hyperparathyroidism (1); Lipid storage disease (1); myopia (1); neurodegenerative disease (1); Onset (1); pancreatic cancer (1); Retinal dystrophy (1).